SSU72L4 (SSU72 like 4)
Description:
Protein phosphatase that catalyzes the dephosphorylation of the C-terminal domain of RNA polymerase II. Plays a role in RNA processing and termination.
Synonyms: SSU72P4
Gene: Protein-coding gene on chromosome 11 (4,287,084 to 4,288,185, reverse strand). Ensembl gene ENSG00000283873.
Subcellular location: Nucleus
Gene Ontology:
Molecular function: protein serine/threonine phosphatase activity; RNA polymerase II CTD heptapeptide repeat phosphatase activity; phosphoprotein phosphatase activity
Biological process: termination of RNA polymerase II transcription; mRNA 3'-end processing; mRNA processing; regulation of transcription by RNA polymerase II
Cellular component: mRNA cleavage and polyadenylation specificity factor complex; nucleus
Homologues: Orthologues: tropical clawed frog ssu72 (67% identical), zebrafish ssu72 (67% identical), Drosophila melanogaster Ssu72 (49% identical), Caenorhabditis elegans ssup-72 (46% identical). Paralogues in human: SSU72L1 (99% identical), SSU72L5 (99% identical), SSU72L2 (98% identical), SSU72L3 (98% identical), SSU72L6 (94% identical), SSU72 (71% identical).